HSPA4L (heat shock protein family A (Hsp70) member 4 like)
Description:
Possesses chaperone activity in vitro where it inhibits aggregation of citrate synthase.
Synonyms: APG1; HSPH3; OSP94; APG-1
Tractability: PROTAC: ubiquitination databases record sites on it; its protein half-life has been measured.
Gene: Protein-coding gene on chromosome 4 (127,781,821 to 127,840,733, forward strand). Ensembl gene ENSG00000164070.
Subcellular location: Cytoplasm; Nucleus
Subcellular location (Human Protein Atlas): Cytosol; Calyx; Centrosome; Perinuclear theca
Pathways (Reactome):
Cellular responses to stimuli: Regulation of HSF1-mediated heat shock response
Gene Ontology:
Molecular function: adenyl-nucleotide exchange factor activity; ATP binding; ATP hydrolysis activity
Biological process: protein folding; response to unfolded protein
Cellular component: cytosol; cytoplasm; nucleus
Genetic constraint (gnomAD): Loss-of-function variants: 22 observed, 57.63 expected, observed/expected ratio (o/e) 0.38, 90% interval 0.27 to 0.55. The upper end of that interval is the gene's LOEUF score, 0.55, which puts it in group 2 of 6, group 1 being the genes least tolerant of losing a copy. Missense variants: 594 observed, 693.78 expected, observed/expected ratio (o/e) 0.86, 90% interval 0.8 to 0.92. Synonymous variants: 214 observed, 233.47 expected, observed/expected ratio (o/e) 0.92, 90% interval 0.82 to 1.03.
Homologues: Orthologues: chimpanzee HSPA4L (99% identical), macaque HSPA4L (98% identical), rabbit HSPA4L (97% identical), dog HSPA4L (96% identical), rat Hspa4l (93% identical), mouse Hspa4l (92% identical), guinea pig HSPA4L (91% identical), pig HSPA4L (90% identical), zebrafish hspa4l (66% identical), Drosophila melanogaster Hsp110 (44% identical), Caenorhabditis elegans hsp-110 (42% identical), Caenorhabditis elegans hsp-70 (23% identical), and 2 more. Paralogues in human: HSPA4 (64% identical), HSPH1 (59% identical), HYOU1 (28% identical), HSPA8 (26% identical), HSPA1L (25% identical), HSPA1A (25% identical), HSPA1B (25% identical), HSPA6 (25% identical), HSPA2 (24% identical), HSPA5 (23% identical), HSPA9 (21% identical), HSPA14 (16% identical), and 1 more.
Diseases named in the same sentence as HSPA4L in open-access papers:
HSPA4L is named in the same sentence as 24 diseases in open-access papers, as found by Europe PMC text mining. Sharing a sentence is not in itself a finding about the gene and the disease. The quoted sentences say what the papers report.
breast carcinoma (2 papers, 2021 to 2022). "HSPA4L mRNA expression was increased in lung squamous cell carcinoma and breast cancer and decreased in prostate adenocarcinoma." (PMID 34712697, 2021).
leukemia (2 papers, 2015). A malignant (clonal) hematologic disorder, involving hematopoietic stem cells and characterized by the presence of primitive or atypical myeloid or lymphoid cells in the bone marrow and the blood. "The role of the heat shock protein HSPA4L is unclear but the gene was found to have a hypermethylated promoter in leukemia cell lines." (PMID 26573568, 2015). "HSPA4L, a member of the Hsp70 family, is highly expressed by leukemia cells and elicits humoral immune responses in leukemia patients." (PMID 26486082, 2015).
lung carcinoma (2 papers, 2015 to 2021). "HSPA14 and HSPA4L were mainly expressed in lung cancer and large intestine cancer cell lines." (PMID 34712697, 2021).
malaria (1 paper, 2024). Malaria is a serious and sometimes fatal disease caused by a parasite that commonly infects a certain type of mosquito which feeds on humans. "Of relevance to the role of HSPs in human malaria pathogenesis, transcripts for HSP60 (HSPD1) were down-regulated in SMA (log2FC = −0.81), as were HSP70 family members: HSPA1A (−1.31), HSPA1B (−0.99), HSPA4 (−0.33), HSPA4L (−0.68), HSPA5 (−0.51), and HSPA6 (−0.81)." (PMID 39452740, 2024).
schizophrenia (1 paper, 2022). A major psychotic disorder characterized by abnormalities in the perception or expression of reality. "Some proteins of the snRNP complex, the core component of the splicing operation, such as heterogeneous nuclear ribonucleoproteins L (HNRNPL), F (HNRNPF), and A2/B1 (HNRNPA2), along with heat shock 70 kDa protein 4L (HSPA4L), were found upregulated in the schizophrenia-derived organoids." (PMID 36451159, 2022).
schwannoma (1 paper, 2013). A benign, usually encapsulated slow growing tumor composed of Schwann cells. "In our series, 5 HSPs were deregulated (HSPA12A: 3.31-fold, p=4.34e-4; HSPA13: 2.54-fold, p=0.0035; HSPA4L: 2.38-fold, p=1.17e-4; HSPB6: −2.19-fold, p=5.76e-4; HSPB8: −3.77-fold, p=0.001), suggesting that the CAV1/HSPs interaction may also play a role in schwannomas." (PMID 23354516, 2013).
uterine corpus endometrial carcinoma (1 paper, 2021). A endometrial carcinoma (disease) that involves the body of uterus. "Notably, the mutation of six HSPs, including HSPA4L, TRAP1, HSPH1, HSP90AA1, HSPA8 and HSPA9, was associated with their protein expression in uterine corpus endometrial carcinoma (p < 0.05)." (PMID 34712697, 2021).
cancer (4 papers, 2015 to 2021). A tumor composed of atypical neoplastic, often pleomorphic cells that invade other tissues. "Based on a literature survey, we focused our attention on ANLN (anillin, actin-binding protein) and HSPA4L (heat shock 70 kDa protein 4–like) because these two genes are up-regulated in many cancers." (PMID 26486082, 2015). "Transfection of a miR-497 mimic or small interfering RNAs (siRNAs) against ANLN and HSPA4L inhibited cancer phenotypes in NPC cells." (PMID 26486082, 2015). "Our findings indicate that miR-497 is a potent tumor suppressor that inhibits cancer phenotypes by targeting ANLN and HSPA4L in NPC." (PMID 26486082, 2015). "MGAT4C, HSPA4L, ZSCAN5A, LOC100505841, and NALCN gene deletions were associated with cancer patients without FCH (p < 0.05), while SMYD3 and NKD2DSV genes were associated with cancer patients with FCH (p < 0.05)." (PMID 33431054, 2021). "HSPA4L showed a particular profile, its expression decreased in HER2 and Luminal A cancers only." (PMID 29954368, 2018).
tumor (4 papers, 2010 to 2025). "Remarkably, we found higher transcript levels of PyMT tumor antigens (Hspa4l, Lyar, Ddx20, Acrbp) in these cells of PyMT-PAR2G37I relative to PyMT-PAR2WT mice, suggesting increased uptake of tumor cell debris, which contains various nucleic acid species." (PMID 40694429, 2025). "In primary NPC tissues, ANLN was expressed in the cytoplasm of NPC tumor cells (left lower), whereas HSPA4L was strongly expressed in the nucleus and cytoplasm of NPC cells and mucosa adjacent to NPC nests (right lower)." (PMID 26486082, 2015). "The up-regulated genes following treatment included heat shock family proteins such as HSP90AA1, HSPA8, DNAJB12, HSPA1L, DNAJA1, HSPA4L, consistently with other array studies in different tumor cell types." (PMID 20920318, 2010). "Similarly, HSPA4L was down-regulated in AGS and U87MG cells, while up-regulated in 5637 tumor cell line." (PMID 26862520, 2016). "Our findings suggest that miR-497 acts as a tumor suppressor by targeting ANLN and HSPA4L in NPC." (PMID 26486082, 2015).
HSPA4L also shares sentences with these, for which no sentence is quoted: asthenozoospermia (1 paper); Azoospermia (1); colorectal cancer (1); endometrial cancer (1); infection (1); Infertility (1); lung squamous cell carcinoma (1); multiple sclerosis (1); nasopharyngeal carcinoma (1); osteosarcoma (1); prostate adenocarcinoma (1); prostate carcinoma (1); renal carcinoma (1); synucleinopathy (1); thyroid cancer (1).